EGR2 (early growth response 2)
Diseases named in the same sentence as EGR2 in open-access papers (continued):
Sharing a sentence is not in itself a finding about the gene and the disease.
thyroid cancer (3 papers, 2021 to 2024). "Here, we shown that miR-17-5p was apparently overexpression, while EGR2 was otherwise significantly down-regulation in thyroid cancer tissues as well as cell lines in comparison with the paired non-tumorl tissues and normal cells." (PMID 34130587, 2021). "Subcutaneous tumorigenesis in nude mice also demonstrated that EGR2 overexpression remarkably inhibited thyroid cancer progression in vivo." (PMID 34130587, 2021). "Due to EGR2 has been shown as a target gene of miR-17-5p, we next study the function of EGR2 in thyroid cancer progression." (PMID 34130587, 2021). "Further, we measured EGR2 expression levels in thyroid carcinoma tissues by WB and immunohistochemistry." (PMID 34130587, 2021). "In thyroid cancer, overexpression of EGR2 can inhibit the progression of the disease." (PMID 38911380, 2024). "miR-17-5p is a thyroid cancer oncomir by modulation of the EGR2." (PMID 34130587, 2021). "Furthermore, the levels of E-cadherin and MAPK in tumor tissues from the miR-17-5p inhibition group were decreased in comparison with the control group, indicating miR-17-5p promote thyroid cancer tumorigenicity by suppressing EGR2." (PMID 34130587, 2021). "In our study, we also found that EGR2 decreased in thyroid cancer tissues and cells." (PMID 34130587, 2021). "Overexpressed EGR2 inhibited the development of thyroid carcinoma both vivo and in vivo." (PMID 34130587, 2021). "miR-17-5p was predicted to bind with EGR2 directly in thyroid carcinoma." (PMID 34130587, 2021). "EGR2 overexpression could suppresses the malignancy of thyroid carcinoma through inhibition of tumor cell proliferation and migration." (PMID 34130587, 2021). "Furthermore, our results indicated EGR2 is the target gene of miR-17-5p in TC, which may supply a promising treatment target for thyroid cancer." (PMID 34130587, 2021).
/T-cell lymphoma (2 papers, 2016 to 2022). "It has indeed been shown that the miR-150 target gene repertoire can highly differ between different hematopoietic malignancies, e.g., MYB, FLT3, CBL and EGR2 in MLL-rearranged AML cells, and DKC1 and AKT2 in NK/T-cell lymphoma." (PMID 35205272, 2022). "MYB, FLT3, and EGR2 have been identified as critical target genes of miR-150 in MLL-rearranged AML, while AKT2 is a direct target of miR-150 in NK/T-cell lymphoma." (PMID 27917123, 2016).
autism (2 papers, 2011 to 2012). Persistent deficits in social interaction and communication and interaction as well as a markedly restricted repertoire of activity and interest as well as repetitive patterns of behavior. "Several genes that are essential for neurological development, such as roundabout, axon guidance receptor, homolog 1 (ROBO1) and early growth response 2 (EGR2) are also differentially expressed in the lympnoblastoid cell lines from monozygotic twins discordant in severity of autism spectrum." (PMID 21935445, 2011).
cervical cancer (2 papers, 2011 to 2024). A primary or metastatic malignant neoplasm involving the cervix. "In cervical cancer, the upregulation of EGR2 may enhance the anti-tumor immune response by promoting the differentiation of T-cells into a more cytotoxic phenotype, which is essential for eliminating cancer cells during therapies such as chemoradiation and immunotherapy." (PMID 39590310, 2024). "Several genes involved in pathways altered in early stages of cervical cancer, such as CASP9 and EGR2 involved in apoptosis and MYC-N, CCNA and RhoA involved in cell proliferation, were altered by HPV16 E2 expression." (PMID 21599968, 2011).
Charcot-Marie-Tooth disease (2 papers, 2016 to 2025). "Egr2 is a transcription factor, and its mutation causes musculoskeletal diseases such as Charcot-Marie-Tooth disease and Dejerine–Sottas disease." (PMID 27164082, 2016).
demyelinating peripheral neuropathies (2 papers, 2010 to 2024). "Mutations in MPZ, SOX10, and EGR2 have been implicated in demyelinating peripheral neuropathies, suggesting that components of this transcriptional network are candidates for harboring disease-causing mutations (or otherwise functional variants) that affect MPZ expression." (PMID 21179557, 2010).
depression (2 papers, 2022 to 2024). "In most of the top models, a consistent dysregulation of MAP kinase pathway was identified and the genes NR4A1, BDNF, ARC, EGR2, and PDE7B were consistently downregulated as in humans with depression." (PMID 34997033, 2022).
influenza (2 papers, 2021 to 2023). An acute viral infection of the respiratory tract, occurring in isolated cases, in epidemics, or in pandemics; it is caused by serologically different strains of viruses (influenzaviruses) designated A, B, and C, has a 3-day incubation period, and usually lasts for 3 to 10 days. "After individual siRNA treatment and then FYW exposure, we found that IFN signaling was still reduced upon influenza exposure, only abrogated by 1.2, 1.3, and 1.4-fold in the case of EGR2, IL31RA, and ATP6VD02, respectively." (PMID 38322710, 2023).
ischemic stroke (2 papers, 2024). A stroke disorder caused by obstruction of blood flow to the brain, due to thrombotic (local blood clot formation) or embolic (due to a blood clot or other material traveling from another site) event. "Early growth response 2 (Egr2) regulates pro-inflammatory cytokines and lessens the impact of ischemic stroke." (PMID 39095888, 2024). "Among them, there may be previously listed Fos, Junb, Jak2, Npas4, Egr2 and other proteins, which may help to validate some key signaling pathways after peptide treatment at the protein level and reveal the potential effects of peptides on ischemic stroke." (PMID 39767736, 2024).
leiomyoma (2 papers, 2017 to 2021). A well-circumscribed benign smooth muscle neoplasm characterized by the presence of spindle cells with cigar-shaped nuclei, interlacing fascicles, and a whorled pattern. "In women, elevated levels of EGR2 mRNAs were identified in leiomyoma smooth muscle cells, whereas a knock-down of EGR2 in these cells is associated with an increased cell proliferation rate." (PMID 34298942, 2021). "Knockdown of EGR2 in leiomyoma cells increased myc and PCNA expression as well as collagen deposition." (PMID 28687085, 2017).
leprosy (2 papers, 2017 to 2023). Leprosy is a chronic infectious disease affecting primarily the skin and peripheral nervous system. "Moreover, signals of DNase‐seq, H3K4me3 ChIP‐seq, or H3K27ac ChIP‐seq were observed in skin or PBMCs in SNPs among the previously identified known leprosy loci, including loci that EGR2, TNFSF15, RAB32, and NOD2 located in." (PMID 38020709, 2023). "The reported peak of association with leprosy per se encompassed the ADO and EGR2 genes." (PMID 28222097, 2017).
liver cancer (2 papers, 2023 to 2024). An epithelial or non-epithelial malignant neoplasm that arises from the liver. "It is downregulated in liver cancer, and overexpression of EGR2 can inhibit the invasive ability of HepG2 liver cancer cells." (PMID 38911380, 2024).
Liver fibrosis (2 papers, 2021 to 2024). "Liver fibrosis was ameliorated in mice deficient in Egr2 in immune cells of myeloid lineage." (PMID 38831027, 2024). "As Egr2 expression level was lower in moKCs than in hLAMs, the downregulation of Egr2 in hLAMs may be associated with the conversion of hLAMs into moKCs and the subsequent amelioration of liver fibrosis." (PMID 38831027, 2024). "Overall, these findings indicate that Egr2 expression in monocyte-derived macrophages is positively correlated with the progression of MASH to liver fibrosis." (PMID 38831027, 2024). "Collectively, these findings indicate that the Egr2 expression by monocytes and macrophages is responsible for the development of liver fibrosis in MASH." (PMID 38831027, 2024). "Thus, although Egr2 might be a target for liver fibrosis in MASH, Egr2 should be targeted selectively in monocytes and macrophages in order not to inhibit protective responses by LAG3+CD4+CD25- regulatory T cells." (PMID 38831027, 2024).
lupus-like syndrome (2 papers, 2015 to 2020). "We identified two molecules, Fasand Egr2, that are required forTGF-β3 secretion inLAG3+ Treg.Egr2 deficiency in T cellsand B cells results in a lupus-like syndrome, and Egr2 directly activates p21cip1 expression inCD44high Tcells and is involved in the control of Th1 and Th17 differentiation." (PMID 25695838, 2015). "Therefore, EGR2 was deleted in T and B lymphocytes only in so-called EGR2 conditional knockout (CKO) mice, and it was shown that these mice developed lupus-like syndromes during maturity." (PMID 33114612, 2020).
multiple sclerosis (2 papers, 2021 to 2024). A progressive autoimmune disorder affecting the central nervous system resulting in demyelination. "And early growth response gene-2 (Egr-2) is an intrinsic regulator that controls Th17 differentiation by inhibiting BATF activation, which may be important in controlling the development of multiple sclerosis." (PMID 35126277, 2021).
neuroblastoma (2 papers, 2014 to 2020). Neuroblastoma (NB) is the most common solid, extracranial childhood tumor. "For this purpose, we analyzed the ability of ectopic Egr2 to induce the expression of its target genes in Neuro2a neuroblastoma cells with varying levels of Rnf40/Rnf20 E3 ligase activity." (PMID 32672815, 2020). "Cytokines selected from primary, secondary, and tertiary clusters with respect to EPO (IL-11, KITLG, LIF, THPO) were chosen as experimental candidates, to test their effect on Egr2 mRNA expression in serum-starved EPOR-B104 neuroblastoma cells exactly." (PMID 24672526, 2014).
papillary thyroid carcinoma (2 papers, 2021 to 2022). "MiR-224-5p has been reported to direct binding with EGR2 to accelerate the progression of papillary thyroid carcinoma." (PMID 34130587, 2021). "Furthermore, EGR2 was found to be decreased in papillary thyroid carcinoma (PTC) tissues and cell lines and EGR2 could promote apoptosis in various cancers." (PMID 34130587, 2021).
polyneuropathy (2 papers, 2013 to 2017). A disease or disorder affecting more than one nerve. "Genetic testing was performed according to polyneuropathy type; demyelinating/mixed: PMP22 duplication, MPZ, EGR2, LITAF, NEFL, PMP22, GJB1, axonal: MFN2, MPZ, NEFL, and GJB1." (PMID 24053775, 2013).
pulmonary fibrosis (2 papers, 2015 to 2024). Chronic progressive interstitial lung disorder characterized by the replacement of the lung tissue by connective tissue, leading to progressive dyspnea, respiratory failure, or right heart failure. "EGR2 is reported to mediate pro-fibrotic actions of TGF-β in pulmonary fibrosis." (PMID 26107172, 2015). "Accordingly, the comparative histological reviews revealed a tendency of nonresolving protracted inflammation with early progressive pulmonary fibrosis in myeloid-specific EGR2-deficient lung samples at day 5 of AF inoculation, which was verified by Masson’s trichrome staining." (PMID 39042472, 2024).
renal cell carcinoma (2 papers, 2021 to 2022). "Interestingly, a study has also reported that EGR2 could increase IGF2BPs expression to enhance the m6A level of sphingosine-1-phosphate receptor 3 to accelerate tumorigenesis and metastasis of renal cell cancer." (PMID 37529797, 2022). "Our studies showed that the EGR2/IGF2BPs regulatory axis and m6A-dependent regulation of S1PR3-driven RCC tumorigenesis, which enrich the m6A-modulated regulatory network in renal cell cancer." (PMID 34326314, 2021).
rheumatoid arthritis (2 papers, 2020). A chronic, systemic autoimmune disorder characterized by inflammation in the synovial membranes and articular surfaces. "PD-1high MP CD4 T cells have recently been implicated in rheumatoid arthritis pathogenesis, and we have now found that Egr2 expression is reduced in PD-1high MP CD4 T cells from patients with active rheumatoid arthritis compared with healthy controls." (PMID 32709717, 2020).
Richter syndrome (2 papers, 2017 to 2020). Transformation of chronic lymphocytic leukemia into aggressive non-Hodgkin's lymphoma, usually diffuse large B-cell lymphoma (immunoblastic or centroblastic variant).
Splenomegaly (2 papers, 2022 to 2023). Abnormal increased size of the spleen. "Consistent with the previous report that EGR2 deletion promoted splenomegaly in B6 mice, we found that EGR2 deletion in B6/lpr mice also significantly increased spleen weight." (PMID 35784356, 2022).
systemic sclerosis (2 papers, 2022). A chronic disorder, possibly autoimmune, marked by excessive production of collagen which results in hardening and thickening of body tissues. "Markedly elevated expression of EGR2 was noted in skin and lung biopsies obtained from systemic sclerosis patients, particularly in BECs and fibroblasts." (PMID 35406678, 2022).
uveitis (2 papers, 2021). An inflammatory process affecting a part of or the entire uvea. "Genome-wide association studies (GWASs) have provided a powerful tool for the genome-wide analysis of genetic susceptibility to uveitis, revealing several genes associated with uveitis, including IL23R/C1ORF141, STAT4, and ADO/ZNF365/Egr2." (PMID 34869347, 2021).
allergic asthma (1 paper, 2019). A asthma with a basis in a pathological type I hypersensitivity reaction. "EGR2 has been shown to be a crucial mediator of allergic asthma, as its expression is necessary in mast cells to direct CD4+ T cell migration to inflamed lung." (PMID 31832069, 2019).
anxiety depression (1 paper, 2024). "Six core mRNAs on which ZZCD works for anxiety depression were obtained by constructing PPI network: Fos, Junb, Egr2, Dusp1, Nr4a1, and Btg2." (PMID 37905694, 2024).
Arthritis (1 paper, 2020). Inflammation of a joint. "The reduced expression of Egr2 coupled with increased T-bet and Granzyme B expression in PD-1high CD4 T cells may serve as one of the molecular signatures for active arthritis." (PMID 32709717, 2020). "In the absence of Egr2/3, PD-1high MP CD4 T cells are highly inflammatory but have impaired homeostasis and T-cell function, a phenotype discovered recently in SLE and arthritis." (PMID 32709717, 2020).
Ataxia (1 paper, 2026). Ataxia refers to impaired coordination of voluntary muscle movement. "However, Egr2 is known to be an important transcription factor in regulating nervous system development and nervous system functions such as memory and learning, and is associated with neurobehavioral abnormalities, memory, and ataxia." (PMID 41438503, 2026).
bladder cancer (1 paper, 2024). "Immunohistochemical results showed that EGR2 was highly expressed in bladder cancer tissues, and its overexpression was associated with poor prognosis." (PMID 38911380, 2024). "We also identified EGR2 as a key gene associated with bladder cancer development and progression." (PMID 38911380, 2024). "Notably, high expression levels of HDAC4 and TRIM27 were identified as favorable prognostic factors for bladder cancer patients, while elevated expression of EGR2 and UBE2I was associated with an unfavorable prognosis." (PMID 38911380, 2024). "The expression of EGR2 in bladder cancer was detected by immunohistochemistry, and the cell function experiment clarified the effect of knocking down EGR2 on the proliferation, invasion, and migration of bladder cancer cells." (PMID 38911380, 2024). "This suggests that HDAC4, TRIM27, EGR2, and UBE2I exhibit a relatively low mutation rate in bladder cancer." (PMID 38911380, 2024). "The results indicated that among 411 cases of bladder cancer, TRIM27 gene mutations were detected in 5 patients, HDAC4 gene mutations in 4 patients, EGR2 mutations in 2 patients, and UBE2I gene mutations in 1 patient." (PMID 38911380, 2024). "Gene mutation analysis indicated a relatively low mutation rate in HDAC4, TRIM27, EGR2, and UBE2I in bladder cancer." (PMID 38911380, 2024). "The results showed that low expression of EGR2 is a favorable prognostic factor for bladder cancer patients." (PMID 38911380, 2024). "Following that, we conducted an in-depth investigation of EGR2 expression in bladder cancer through immunohistochemistry." (PMID 38911380, 2024). "Our experimental findings unveiled a significant upregulation of EGR2 protein expression in bladder cancer tissues as compared to adjacent tissues." (PMID 38911380, 2024). "We evaluate the expression of EGR2 protein in 80 paired bladder cancer samples, encompassing both cancerous and adjacent tissues." (PMID 38911380, 2024). "Survival analysis provided additional evidence that high expression of EGR2 protein is an unfavorable prognostic factor for patients with bladder cancer." (PMID 38911380, 2024). "We identified four key genes, HDAC4, TRIM27, EGR2, and UBE2I, that exhibited significant associations with bladder cancer prognosis." (PMID 38911380, 2024). "Our findings demonstrated that four genes, HDAC4, TRIM27, EGR2, and UBE2I, exhibited significant associations with bladder cancer prognosis." (PMID 38911380, 2024). "Knockdown of EGR2 inhibited proliferation, invasion, and migration of bladder cancer cells, highlighting its functional role in the disease." (PMID 38911380, 2024). "Immunohistochemistry analysis further confirmed that EGR2 expression was substantially upregulated in bladder cancer tissues compared to adjacent normal tissues, suggesting a potential role for EGR2 in bladder cancer development or progression." (PMID 38911380, 2024). "We examined EGR2 expression in bladder cancer tissues and adjacent normal tissues and investigated its functional role in bladder cancer cell lines through knockdown experiments." (PMID 38911380, 2024). "In addition, we further analyzed the prognostic value of EGR2 in bladder cancer patients using the TCGA, GSE32894, and GSE48075 cohorts." (PMID 38911380, 2024). "Finally, we focused on the role of EGR2 in bladder cancer and demonstrated its impact on cell proliferation, invasion, and migration." (PMID 38911380, 2024). "Furthermore, we focused on the functional significance of Early Growth Response 2 (EGR2), one of the identified SPRG associated with bladder cancer prognosis." (PMID 38911380, 2024). "Knockdown of EGR2 inhibited bladder cancer cell proliferation, invasion, and migration." (PMID 38911380, 2024). "Additionally, we identified EGR2 as a key SPRG in bladder cancer." (PMID 38911380, 2024).
bladder cancer (continued). "To gain further insights into the functional impact of EGR2 in bladder cancer cells, we conducted targeted experiments to knock down EGR2 expression in RT4 and T24 bladder cancer cell lines." (PMID 38911380, 2024). "The identification of EGR2 as a key SPRG and its functional impact on bladder cancer cells further highlights its significance in bladder cancer development and progression." (PMID 38911380, 2024). "We analyzed gene expression and prognostic value of SPRG and developed a SPRG signature (SPRGS) prognostic model based on four genes (HDAC4, TRIM27, EGR2, and UBE2I) in bladder cancer." (PMID 38911380, 2024). "Finally, random forest analysis identified EGR2 as the most significant gene among the four SPRG examined, highlighting its potential importance in bladder cancer." (PMID 38911380, 2024).
Burkitt lymphoma (1 paper, 2019). A rare form of malignant mature B-cell non-Hodgkin lymphoma. "Of note, EGR2 mutations have been detected in clinically aggressive CLL subgroups while E2F4, a key regulator of the cell cycle, has been reported deregulated in both Burkitt lymphoma and diffuse large B cell lymphoma." (PMID 31791414, 2019).